PLK4 (polo like kinase 4)
Diseases named in the same sentence as PLK4 in open-access papers (continued):
Sharing a sentence is not in itself a finding about the gene and the disease.
tumor (continued). "Expression analysis further revealed that Plk4 mRNA was not significantly increased in freshly isolated tumor cells from EμMYC/Plk4 mice." (PMID 38552015, 2024). "We obtained 75 paired CRC patient-matched tumor and adjacent non-tumor tissue specimens among the 122 patients, these specimens further confirmed that PLK4 expression was significantly higher in CRC tissues." (PMID 37324947, 2023). "Our data show that high Plk4 expression is associated with malignant features such as anoikis resistance and EMT in cancerous and non-cancerous cells in the tumor microenvironment, endorsing its role in tumor initiation and/or progression." (PMID 36797240, 2023). "Initial attempts to overexpress Plk4 failed to induce accelerated development of tumours, despite observing supernumerary centrosomes and a high incidence of aneuploidy in affected tissues." (PMID 35164835, 2022). "A recent study suggested that targeting Polo-like kinase 4 (PLK4), a centrosome duplication regulator, could suppress tumor proliferation via inhibiting the cell cycle and eliciting anti-tumor immunity, with durable effect even in late-stage mouse HCC." (PMID 36238304, 2022). "Since STIL is a master regulator of PLK4, we speculate that a low-to-moderate level of STIL could promote tumor initiation, as seen for PLK4, via a yet-unknown mechanism." (PMID 35365182, 2022). "Another Plk4 inhibitor CFI-400945 also triggered mitotic defects in MDA-MB-468 and MDA-MB-231 cells by the dysregulation of centriole number and the induction of polyploidy and inhibited tumor growth in xenograft mouse model established with MDA-MB-468 cells." (PMID 33777739, 2021). "Higher expression level of PLK4 was found in NB liver metastasis tissues, rather than primary tumor tissues." (PMID 29352113, 2018). "In 13 out of 20 cases, PLK4 mRNA was downregulated in tumor tissues, compared with the adjacent nontumorous tissues." (PMID 22829937, 2012). "Independent of its role in centrosome biogenesis, PLK4 may also impact the tumor microenvironment to promote malignancy." (PMID 41092110, 2025). "They showed that FAM46C functions as a tumour suppressor by inhibiting centriole over-duplication, an event often seen in cancer cells, by blocking the autophosphorylation capacity of PLK4 in a way that is totally independent of its poly(A) polymerase activity." (PMID 38730656, 2024). "To further examine the therapeutic potential of targeting PLK4 to antagonize oxaliplatin resistance, we set up a tumor xenograft model in mice with oxaliplatin-responsive (vector) or -resistant (HCT116OR) HCT116 cells and monitored in vivo tumor growth upon oxaliplatin or CFI-400945 treatment." (PMID 38951519, 2024). "Besides, PLK4 might induce epithelial-mesenchymal transition (EMT) by regulating the Wnt/β‐catenin signaling pathway, enhancing tumor invasion and metastasis." (PMID 38326803, 2024).
tumor (continued). "Notably, we found that the expression of PLK4 was markedly correlated with Ki67 expression level (p < 0.001), tumor size (p = 0.041), TMN stage (p = 0.002), CEA (p = 0.016), lymph node metastasis status (p = 0.012) and tumor capsule status (p = 0.001)." (PMID 37324947, 2023). "Importantly, we demonstrate that talazoparib‐induced lncRNA PLK4 could inhibit YAP signalling to further promote HepG2 cell senescence, which is the vital molecular mechanism that drug suppresses tumour cell proliferation." (PMID 32243714, 2020). "Furthermore, PLK4 expression and those clinicopathologic variables significant in univariate analysis (i.e., serum AFP level, tumor size, tumor multiplicity, tumor differentiation, clinical stage and vascular invasion) were further evaluated in multivariate analysis." (PMID 22829937, 2012). "Furthermore, PLK4 expression significantly correlated with clinicopathological parameters, including clinical stage (P = 0.034), serum α-fetoprotein (AFP) (P = 0.019) and tumor size (P = 0.032)." (PMID 22829937, 2012). "Despite the reported pro-cancerogenic effects of extra centrosomes, we did not observe any difference in tumor latency in oncogene-driven blood cancer induced by the overexpression of MYC or ABL kinase, when combined with continued Plk4 transgene expression." (PMID 38552015, 2024). "We first wished to address the effects of Plk4 over-expression upon tumour formation and so carried out parallel studies on the viability of the Plk4OE/Plk4OE line with or without the addition of doxycycline (+DOX) to promote Plk4 over-expression." (PMID 26701933, 2015).
infection (4 papers, 2013 to 2024). The state of being infected such as from the introduction of a foreign agent such as serum, vaccine, antigenic substance or organism. "Following infection, new centrioles appear rapidly in MEFs at the base of the existing mother and daughter centrioles, forming a flower-like arrangement that can also arise during the cell cycle when Plk4, or Sas-6 are overexpressed." (PMID 30120325, 2018). "Of the 17 HPK genes identified important for A/WSN/33 replication, six (CDK13, HK2, NEK8, PANK4, PLK4, SGK3) emulated the phenotype following A/New Caledonia/20/99 infection, i.e. increased or decreased virus replication as measured by influenza NP localization and influenza M gene levels." (PMID 23805279, 2013). "While the loss of Plk4 did not significantly affect IgM immunoglobulin levels, representing largely natural antibodies that are produced in the absence of infection, IgG1 levels clearly dropped in Plk4 mutant mice, but were back to normal when Usp28 was co-deleted and B cell maturation restored." (PMID 39406735, 2024).
blood cancer (1 paper, 2024). "While Plk4 overexpression does not affect oncogene-driven blood cancer, lymphomagenesis and fibrosarcoma formation initiated by DNA damage are found delayed in the presence of a functional PIDDosome." (PMID 38552015, 2024).
CNS) tumors (1 paper, 2019). "A brain penetrant PLK4i could be used to treat not only EBT but other aggressive CNS tumors with PLK4 overexpression like GBM." (PMID 31035676, 2019).
PLK4 also shares sentences with these, for which no sentence is quoted: cutaneous melanoma (3 papers); brain cancer (2); Central Nervous System Neuroblastoma (2); Fanconi anemia (2); hypogonadism (2); lung squamous cell carcinoma (2); metastasis (2); retinitis pigmentosa (2); Sertoli Cell-Only Syndrome (2); teratozoospermia (2); triple-negative breast carcinoma (2); acute lymphoblastic leukemia (1); adenocarcinoma of the cervix (1); autosomal recessive primary microcephaly (1); bile duct cancer (1); brain edema (1); cardiovascular diseases (1); colon (1); colorectal adenocarcinoma (1); congenital stationary night blindness (1); cutaneous squamous cell carcinoma (1); diabetes (1); diabetic retinopathy (1); dwarfism (1); endometrial tumors (1); endometrioid carcinoma (1); esophageal cancer (1); fibrosis (1); ganglioneuroblastoma (1); ganglioneuroma (1).
A further 23 diseases each share a sentence with PLK4 in 1 paper.